RAC1 (Rac family small GTPase 1)
Diseases named in the same sentence as RAC1 in open-access papers (continued):
Sharing a sentence is not in itself a finding about the gene and the disease.
depression (15 papers, 2013 to 2024). "Given the established association between Rac1 activity in the NAc and depression-like behaviors, as well as spine remodeling due to early life stress, we further investigated Rac1’s involvement in the antidepressant effects of SNS." (PMID 38026979, 2023). "Rac1 signaling has also been implicated in stress-induced depression and the antidepressant-like effects of ketamine." (PMID 36519542, 2022). "Furthermore, knockout of the Rac1 gene and the overexpression of dominant negative Rac1 through herpes-simplex virus-mediated manipulation robustly induces susceptibility to depression-related phenotypes in mice, such as anhedonia and social avoidance." (PMID 37445914, 2023). "It has been shown that chronic social stress triggers a reduction in NAc Rac1 expression and that a decrease in Rac1 activity contributes to depression-like behavior and mediates the increase of stubby spines in the NAc." (PMID 38026979, 2023). "Repeated exposure to chronic unpredictable mild stress (CUMS, a valid depression paradigm) downregulates the expression and active form of hippocampal Rac1 in the rat." (PMID 37445914, 2023). "Taken together, our evidence further supports the important role of rac1 in spine remodeling and the treatment of depression, especially in adolescent depressive patients who have experienced early life stress." (PMID 38026979, 2023). "Viral-mediated gene transfer of Rac1 was used to investigate its role in ELS-induced depression-like behaviors in adolescence." (PMID 38026979, 2023). "Transcriptional profiling in chronic social defeat stress-induced depression mice reveals a marked downregulation of Rac1 levels in the NAc, which are correlated with enduring social avoidance behavior." (PMID 37445914, 2023). "Conversely, the viruses-mediated overexpression of constitutively active Rac1 after chronic social defeat reverses depression-related behavior with a restoration of Rac1 levels." (PMID 37445914, 2023). "Rac1 plays a significant role in several psychiatric disorders, such as addiction and depressive disorder." (PMID 38026979, 2023). "Over time, evidence has suggested that Rac1 plays a significant role in several psychiatric disorders, such as addiction and depressive disorder." (PMID 38026979, 2023). "In mice that underwent social defeat, a model of depression-like behavior, Rac1 mRNA level is downregulated." (PMID 32362820, 2020). "Expression in the NAc of constitutively active Rac1 after chronic social defeat stress reversed the induction of stubby spines and depression-related behaviors in mice." (PMID 32362820, 2020). "Our evidence suggests that both DHCA and Mal-gluc contribute to resilience against the development of depression-like phenotypes by modulating, respectively, pathological mechanisms relating to IL-6 and Rac1." (PMID 29396460, 2018). "We showed that downregulation of Rac1 is necessary and sufficient for social avoidance behavior and that pharmacological modulation of Rac1 attenuated stress-induced depression phenotypes." (PMID 29861834, 2018). "Collectively, these data demonstrate that IL-6 and Rac1 can each modulate synaptic plasticity in neurons from NAc, supporting these mechanisms as targets for stress-induced depression." (PMID 29396460, 2018). "Moreover, TG2 may be a factor in the serotonin deficiency associated with major depressive disorder: increased levels of TG2 probably convert serotonin to Rac1, resulting in decreased levels of serotonin and BDNF that are associated with major depressive disorder." (PMID 23503168, 2013). "We further evaluated the role of Rac1 in ELS induced-depression-like behaviors." (PMID 38026979, 2023). "In brief, these studies suggest that abnormal Rac1-dependent intrinsic forgetting may be involved in depression-related phenotypes in mammalian animals, including humans." (PMID 37445914, 2023).
depression (continued). "Here we test the efficacy of BDPP and two novel phytochemicals derived from post-absorptive and microbiome metabolism of BDPP in attenuating depression by reversing stress-mediated brain synaptic maladaptation through modulation of peripheral IL-6 and Rac1 in the NAc." (PMID 29396460, 2018). "A recent study also showed that both chronic social defeat in mice and depression in humans reduced the expression of the RAS-related C3 botulinum toxin substrate 1 (Rac1) gene in the nucleus accumbens, through a mechanism involving increased histone H3 lysine 9 dimethylation." (PMID 27057367, 2016). "Impaired Rac1 function in dendritic arborization and spines have been reported in the post-mortem brain of MDD patients, and rodent models of depression." (PMID 27634008, 2016). "We for the first time report that KOR activation causes changes in BDNF and Rac1 expression, which are considered as neurobiological markers of depression, but hippocampal level of these markers do not match with behavioral response to antidepressants in this model." (PMID 27634008, 2016). "Therefore, we hypothesized that KOR induced NR2B signaling might perturb Rac1 expression and/or activity in this model of depression." (PMID 27634008, 2016). "The administration of S-Ketamine, a rapid and long-lasting antidepressant drug, reverses the reductions in expression and activity of hippocampal Rac1 and rescues CUMS-evoked LTP damage and depression-like behavior." (PMID 37445914, 2023). "Of relevance to the findings reported here, in a recent study using a rat model of depression, PAK1 gene expression was downregulated in the hippocampus whereas the Rac1 gene was upregulated in the amygdala." (PMID 35592113, 2022). "OST treatment improved cognitive deficit, alleviated anxiety- and depression-like behaviors induced by OVX, and reversed OVX-induced alterations in the levels of synaptic proteins and ERα, BDNF, TrKB, p-CREB, p-Akt and Rac1 in the hippocampus." (PMID 34025413, 2021). "We previously found that, in both humans and rodents, chronic stress reduces the expression of RAS-related C3 botulinum toxin substrate 1 (Rac1) in the NAc and stress-mediated downregulation of Rac1 in the NAc correlates with social avoidance behavior in the RSDS model of depression." (PMID 29861834, 2018). "In agreement to these studies in various rodent models of “Major Depression”, we also observed a significant decrease in Rac1 expression in the hippocampus, while no change in the frontal cortex." (PMID 27634008, 2016). "However, the protective role of Rac1 has not yet been examined in an animal model of adolescent depression." (PMID 38026979, 2023). "In addition, endocytosis is postulated to play a role in release site clearance as the perturbation of endocytosis increases the rate of synaptic depression and slows RRP recovery which we did not observe in the Rac1−/− calyces." (PMID 36214784, 2022).
glomerulosclerosis (15 papers, 2013 to 2026). A hardening of the kidney glomerulus caused by scarring of the blood vessels. "We reported previously that Rac1 hyperactivation in podocytes causes proteinuria and glomerulosclerosis in mice." (PMID 36333327, 2022). "p38MAPK is activated in podocytes upon induction with a constitutively active form of Rac1, while a p38 inhibitor can attenuate proteinuria, podocyte loss, and glomerulosclerosis." (PMID 33343355, 2020). "RhoGDI-α deficient mice, which show increased Rac1 activation in the kidneys, were found to develop proteinuria, foot process (FP) effacement, and glomerulosclerosis indicating severe podocyte damage." (PMID 29567961, 2018). "We and others showed that Rac1 hyperactivation in podocytes induces podocyte foot process effacement and, if sustained, podocyte loss and glomerulosclerosis." (PMID 29415466, 2018). "Taken together, these data indicate that Rac1-associated mTOR activation in podocytes plays an important role in preventing the kidneys from developing glomerulosclerosis." (PMID 29567961, 2018). "We administered ADR, which causes podocyte loss from the GBM and glomerulosclerosis, to both Rac1 cKO mice and control mice." (PMID 29567961, 2018). "It is conceivable that in the context of TGFβ1 overproduction in the glomerulus, e.g., diabetic nephropathy, TGFβ1 activates Rac1 in podocytes, ultimately leading to podocyte loss and glomerulosclerosis." (PMID 29415466, 2018). "Previous studies showed that hyperactivation of the RhoGTPase, Rac1, in podocytes causes podocyte injury and glomerulosclerosis (accumulation of extracellular matrix in the glomerulus)." (PMID 29415466, 2018). "Rac1 and mTOR require each other to maintain homeostasis in podocytes and exhibit potential as therapeutic targets for glomerulosclerosis." (PMID 29567961, 2018). "Here, we demonstrated that Rac1 deletion induced podocyte loss and glomerulosclerosis in mice with adriamycin (ADR)-induced nephropathy, and we addressed the role of Rac1 in podocytes during the process of glomerulosclerosis development." (PMID 29567961, 2018). "The ratio of glomerulosclerosis was significantly higher in Rac1 cKO than in control mice (0.56 ± 0.23% in control mice versus 19.12 ± 3.85% in Rac1cKO mice, p < 0.001)." (PMID 29567961, 2018). "Therefore, hyper-activation of Rac1 owing to RhoGDIα inactivation in podocytes triggers MR signaling, promoting podocyte injury and glomerulosclerosis." (PMID 37175424, 2023). "Recent studies have also reported that Rac1, a member of the Rho family GTPases activated by high salt intake, activates mineralocorticoid receptor without aldosterone, in turn inducing salt-sensitive hypertension, proteinuria, and glomerulosclerosis." (PMID 33671239, 2021). "In summary, our data demonstrate that, in injured podocytes, the presence of Rac1 promotes mTOR activation so that remaining podocytes could maintain their size to protect the kidneys from developing glomerulosclerosis." (PMID 29567961, 2018). "To investigate the role of Rac1 expression in podocytes under pathological conditions, we used podocyte-specific Rac1 conditional knock-out (cKO) mice administered adriamycin (ADR), which causes nephrosis and glomerulosclerosis." (PMID 29567961, 2018). "We speculate that Trio may have dual roles; it may play important roles in podocyte development but it may also regulate pathological Rac1 hyperactivation in the context of TGFβ1-mediated podocyte injury and glomerulosclerosis." (PMID 29415466, 2018). "In hyperhomocysteinemia mice, intraperitoneal administration of a Rac1 activator (UTP) promoted whereas a Rac1 inhibitor (NSC-23766) blocked inflammasome activation, podocyte injury, and glomerulosclerosis." (PMID 36017003, 2022).
glomerulosclerosis (continued). "SuPAR activates podocyte αvβ3 integrin and receptor for advanced glycation end-products, now identified as an obligate coreceptor, triggering a Rac1/NOX2-Src-TRPC6 (transient receptor potential canonical channel 6) cascade that produces proteinuria and glomerulosclerosis." (PMID 42313902, 2026). "Recent studies have indicated that podocyte-specific deletion of Cdc42 in vivo, but not of RhoA or Rac1, leads to congenital nephrotic syndrome and glomerulosclerosis." (PMID 26986510, 2016). "Indeed, pronounced glomerulosclerosis was present in glomeruli of 5/6Nx mice without treatment and this was attenuated by Rac-1 and ROCK inhibition as demonstrated with the PAS staining." (PMID 24244677, 2013).
liver fibrosis (15 papers, 2015 to 2026). "MALAT1 also acts as a ceRNA to sponge miR-101b, which mediates Rac1 expression contributing to liver fibrosis." (PMID 32413995, 2020). "The treatment with atorvastatin ameliorated liver fibrosis in the BDL+At group by the down-regulation of Rac1-GTP, Rac1, and NOX1, as well as the elevation of antioxidant molecules (thiols, SOD, and catalase)." (PMID 32395205, 2020). "miR-150 and miR-194 inhibit the activation of hepatic stellate cells by inhibiting the expression of c-MYB and RAC1, leading to the reduction of collagen deposition in liver fibrosis." (PMID 31949877, 2019). "For instance, metastasis-associated lung adenocarcinoma transcript 1 (MALAT1) contributes to liver fibrosis via the regulation of RAS-related C3 botulinum substrate 1 (Rac1) and miR-101b." (PMID 27610008, 2016). "Pharmacological inhibition of the Rac1/JNK pathway attenuated hepatic fibrosis and prevented CCl4-induced carcinogenesis in gankyrinhep mice." (PMID 25950481, 2015). "As gankyrinhep mice displayed persistent Rac1/JNK activation during CCl4 handling, it seems likely to account for the elevated susceptibility of gankyrinhep mice to CCl4-induced liver fibrosis and hepatocarcinogenesis." (PMID 25950481, 2015). "As M2 macrophages are crucial for tissue‐repair, and probably in F. hepatica‐related liver fibrosis, RAC1 could be a key regulator induced by FhEVs in this process." (PMID 37073796, 2023). "Ask1 inhibition reduces kidney and liver fibrosis Cdc42 and Rac1 mediate JNK activation in the context of polycystin overexpression in cells and activate Mlk2 and Mlk3 However, in our model, Ask1 deletion or double deletion of Mlk2 and Mlk3 did not reduce cystic burden in Pkd2 mutants." (PMID 34962918, 2021). "Recent observations have demonstrated that the activity of the Rac1 protein causes the overproduction of ROS-induced NOX1 activation a then increased HSCs activity, which is thought to play a detrimental role in carbon tetrachloride-induced liver fibrosis." (PMID 32395205, 2020). "We have demonstrated that Rac1 is involved in NOX activation and that NOX4/ROS can also induce HSC activation by activating the RhoA/ROCK1 signaling pathway, thereby promoting liver fibrosis." (PMID 32083022, 2020). "Our results showed that atorvastatin treatment notably ameliorated hepatic fibrosis, accompanied by the decreased expression of NOX1, Rac1-GTP, and Rac1 in a rat model of BDL." (PMID 32395205, 2020). "In HSCs, experimental downregulation of augmenter of liver regeneration (ALR) can naturally occur in the process of liver fibrosis, and promote the expressions of Col I, α-SMA, and ras-related C3 botulinum toxin substrate 1 (rac1), which is correlated with microRNA-181a induced by TGF-β124." (PMID 38385079, 2024). "Once Rac1 becomes activated, it incites the activation of NOX1 in which the activated NOX1 facilitates the conversion of HSCs into MF cells, subsequently leading to hepatic fibrosis." (PMID 32395205, 2020). "In addition to regulating profibrogenic genes, 3D-Exo also significantly reduced gene expression of the common markers of cell proliferation (CYCLIND, RAC1 and CDC42) in activated LX2 cells, which are usually upregulated in activated stellate cells during liver fibrosis." (PMID 34930304, 2021).
Parkinson disease (14 papers, 2012 to 2025). A progressive degenerative disorder of the central nervous system characterized by loss of dopamine producing neurons in the substantia nigra and the presence of Lewy bodies in the substantia nigra and locus coeruleus. "WIN55 treatment in a Parkinson's disease model reduced the translocation of NOX‐2 subunits Rac‐1 and p47phox to the plasma membrane." (PMID 40245261, 2025). "HACE1, which is a post-transcriptional regulator of RAC1, governs RAC1 activity by inducing its ubiquitination and subsequent degradation 7, a phenomenon observed in Parkinson's disease." (PMID 38706891, 2024). "Overexpression of miR-133a inhibits autophagy by downregulating ras-related C3 botulinum toxin substrate 1 (RAC1) in Parkinson’s disease in vitro." (PMID 35012539, 2022). "The protective function of Rac1 also extends to Parkinson's disease, a neurodegenerative locomotive, cognitive and behavioral disorder that is caused by the degeneration of the nigrostriatal dopaminergic neurons of the midbrain." (PMID 27442895, 2017). "Monocytic genes highly expressed by AMC (Cxcr4, Csk and Rac1) are known to be involved in several disease pathways such as Parkinson’s disease, Huntington’s disease and HIV infection, phagocytosis and chemokine signaling pathways." (PMID 22697290, 2012). "To unveil the participation of the Rho GTPase family to the molecular pathogenesis of Parkinson’s disease, we first used C elegans to demonstrate the role of the small GTPase RAC1 (ced-10 in the worm) in maintaining dopaminergic function and survival in the presence of alpha-synuclein." (PMID 29429047, 2018). "Further, by using dopaminergic neurons derived from patients of familial LRRK2-Parkinson’s disease we report that human RAC1 activity is essential in the regulation of dopaminergic cell death, alpha-synuclein accumulation, participates in neurite arborization and modulates autophagy." (PMID 29429047, 2018). "This suggests that, similar to ALS, Parkinson's disease progression might require diminished Rac1 activity." (PMID 27442895, 2017).